THUMPD1 (THUMP domain 1 NAT10 acetyltransferase adaptor )
Description:
Functions as a tRNA-binding adapter to mediate NAT10-dependent tRNA acetylation modifying cytidine to N4-acetylcytidine (ac4C).
Synonyms: FLJ20274; Tan1; NEDSOA
Tractability: PROTAC: ubiquitination databases record sites on it; its protein half-life has been measured.
Gene: Protein-coding gene on chromosome 16 (20,702,816 to 20,742,084, reverse strand). Ensembl gene ENSG00000066654.
Subcellular location (Human Protein Atlas): Cytosol
Pathways (Reactome):
Metabolism of RNA: rRNA modification in the nucleus and cytosol
Gene Ontology:
Molecular function: protein binding; RNA binding
Biological process: tRNA modification
Cellular component: nucleoplasm
Genetic constraint (gnomAD): Loss-of-function variants: 31 observed, 29.67 expected, observed/expected ratio (o/e) 1.04, 90% interval 0.78 to 1.41. The upper end of that interval is the gene's LOEUF score, 1.41, which puts it in group 5 of 6, group 1 being the genes least tolerant of losing a copy. Missense variants: 444 observed, 414.62 expected, observed/expected ratio (o/e) 1.07, 90% interval 0.99 to 1.16. Synonymous variants: 165 observed, 154.45 expected, observed/expected ratio (o/e) 1.07, 90% interval 0.94 to 1.22.
Homologues: Orthologues: chimpanzee THUMPD1 (99% identical), macaque THUMPD1 (98% identical), dog THUMPD1 (90% identical), pig THUMPD1 (89% identical), rat AABR07005588.1 (84% identical), mouse Thumpd1 (84% identical), tropical clawed frog thumpd1 (56% identical), zebrafish thumpd1 (43% identical), Drosophila melanogaster CG15014 (29% identical), Caenorhabditis elegans W02G9.3 (18% identical).
Diseases named in the same sentence as THUMPD1 in open-access papers:
THUMPD1 is named in the same sentence as 33 diseases in open-access papers, as found by Europe PMC text mining. Sharing a sentence is not in itself a finding about the gene and the disease. The quoted sentences say what the papers report.
breast carcinoma (3 papers, 2017 to 2025). "To test this hypothesis, we examined THUMPD1 expression and localization in breast cancer tissues and investigated associations between THUMPD1 subcellular localization and patient clinicopathological factors." (PMID 28076326, 2017). "In cultured breast cancer cells, endogenous THUMPD1 also localized to both the cytoplasm and nucleus." (PMID 28076326, 2017). "Treatment with the AKT inhibitor, LY294002, reduced the effects of THUMPD1 overexpression in breast cancer cells." (PMID 28076326, 2017). "All breast cancer cell lines were positive for THUMPD1 expression, whereas the normal breast ductal cell line, MCF-10A, showed only weak expression." (PMID 28076326, 2017). "THUMPD1 overexpression enhanced breast cancer cells invasion and migration in vivo and in vitro, possibly through activation of AKT, GSK3β and Snail, and inhibition of E-cadherin." (PMID 28076326, 2017). "In conclusion, we observed THUMPD1 overexpression in the cytoplasm of breast cancer cells, which positively correlated with high TNM stage, lymph node metastasis, and poor patient prognosis." (PMID 28076326, 2017). "Immunohistochemical analysis of 146 breast cancer specimens (82 triple-negative and 64 non-triple-negative cases) indicated THUMPD1 expression is higher in breast cancer tissues (60.9%, 89/146) than normal breast tissues (28.3%, 15/53; p < 0.001)." (PMID 28076326, 2017). "Our in vivo and in vitro experiments indicated that THUMPD1 enhanced breast cancer cells invasion and migration." (PMID 28076326, 2017). "THUMPD1 promoted breast cancer cells invasion and migration, and downregulated E-cadherin via the AKT-GSK3β-Snail pathway, illuminating a possible mechanism underlying THUMPD1 in breast cancer progression." (PMID 28076326, 2017). "Our preliminary experiments showed that THUMPD1 expression was elevated in breast carcinoma samples as compared to normal breast tissues." (PMID 28076326, 2017). "Breast cancer cells exhibited both cytosolic and nuclear THUMPD1 expression, with only nuclear expression in MCF-10A cells." (PMID 28076326, 2017). "Cytosolic and nuclear THUMPD1 expression frequency were 37% and 37.7%, respectively, in breast cancers, and 24.5% (p = 0.093) and 5.6% (p < 0.001), respectively, in normal breast tissues." (PMID 28076326, 2017). "For instance, the parallels between embryonic development and cancer metastasis led us to carry out a pilot study in which heterozygous Thumpd1+/− mice - which harbor quantitatively lower levels of tRNA ac4C – were crossed into a model of breast cancer metastasis." (PMID 39091849, 2024). "MG132, a proteasome inhibitor, further enhanced Snail expression, suggesting that THUMPD1 may stabilize Snail to promote breast cancer cells invasion." (PMID 28076326, 2017). "However, THUMPD1 downstream signaling pathways in human breast cancer are as yet largely unknown." (PMID 28076326, 2017). "We performed immunohistochemistry to assess THUMPD1 expression in 146 breast cancer and 53 paired noncancerous specimens." (PMID 28076326, 2017). "Overall and cytosolic, but not nuclear, THUMPD1 expression in breast cancer correlated with advanced TNM stage (p = 0.003 and p < 0.001, respectively), lymph node metastasis (p = 0.001 and p < 0.001, respectively), and poor patient prognosis (p = 0.001 and p < 0.001, respectively)." (PMID 28076326, 2017). "However, subsequent cox univariate (UA) and multivariate (MA) analyses revealed that cytosolic overexpression of THUMPD1 could not be considered an independent prognostic factor in breast cancer (p = 0.001 for UA, and p = 0.146 for MA)." (PMID 28076326, 2017). "We analyzed expression of proteins involved in breast cancer cell epithelial-mesenchymal transition (EMT), with or without THUMPD1 overexpression or knockdown." (PMID 28076326, 2017).
Intellectual disability (2 papers, 2023 to 2025). "Biallelic variants in THUMPD1 cause a loss of tRNA N4-acetylcytidine modification (ac4C) function and lead to global developmental delay, speech delay, intellectual disability, behavioral abnormalities, facial dysmorphism, and ophthalmological abnormalities." (PMID 41191133, 2025).
carcinoma in situ (1 paper, 2017). "THUMPD1 presented negative or weak nuclear expression in normal breast tissues, moderate nuclear expression in carcinoma in situ samples, and strong nuclear expression in IDCs, which also showed positive THUMPD1 cytosolic expression." (PMID 28076326, 2017).
colorectal cancer (1 paper, 2021). A primary or metastatic malignant neoplasm that affects the colon or rectum. "According to pan-cancer analysis of NAT10, the partner of THUMPD1 for mRNA acetylation, high NAT10 expression is associated with worse survival in LIHC, lymphoma and colorectal cancer." (PMID 34762107, 2021).
endocervical carcinoma (1 paper, 2021). A carcinoma that arises from epithelial cells of the endocervix. "The cervical and endocervical cancers (CESC), kidney renal papillary cell carcinoma (KIRP), rectum adenocarcinoma (READ) and uterine carcinosarcoma (UCS) cohorts shared similar THUMPD1 expression compared with para-cancerous normal tissues." (PMID 34762107, 2021).
lung squamous cell carcinoma (1 paper, 2021). "Lower THUMPD1 expression was observed in bladder urothelial carcinoma (BLCA), KIRC, lung squamous cell carcinoma (LUSC), ovarian serous cystadenocarcinoma (OV) and uterine corpus endometrial carcinoma (UCEC) cohorts." (PMID 34762107, 2021).
lymph node metastasis (1 paper, 2017). "Statistical analyses revealed that overall and cytosolic THUMPD1 expression correlated with high TNM stage (p = 0.003 and p < 0.001, respectively) and lymph node metastasis (p = 0.001 and p < 0.001, respectively)." (PMID 28076326, 2017). "THUMPD1 is also expressed in the cytoplasm of IDC cells, and cytosolic THUMPD1 expression positively correlated with high TNM stage, lymph node metastasis, and poor patient prognosis." (PMID 28076326, 2017).
paraganglioma (1 paper, 2021). A benign or malignant neoplasm arising from paraganglia located along the sympathetic or parasympathetic nerves. "The results showed a co-expression with THUMPD1 in almost all cancer types (except for ACC, BRCA, kidney chromophobe (KICH) and LAML), among which the correlation coefficient was highest in THCA, UVM, PAAD, pheochromocytoma and paraganglioma (PCPG) and DLBC." (PMID 34762107, 2021).
rectal cancer (1 paper, 2021). A primary or metastatic malignant neoplasm that affects the rectum. "In particular, elevated expression of THUMPD1 largely improved the survival probability of patients with READ, suggesting THUMPD1 as a potential favorable prognostic indicator for rectal cancers." (PMID 34762107, 2021).
rectum adenocarcinoma (1 paper, 2021). An adenocarcinoma arising from the rectum. "In kidney renal clear cell carcinoma (KIRC) and rectum adenocarcinoma (READ), patients with higher THUMPD1 expression exhibited a better prognosis, while liver hepatocellular carcinoma (LIHC) patients had worse prognosis." (PMID 34762107, 2021).
tumor (8 papers, 2017 to 2026). "Besides, THUMPD1 was significantly associated with immune cell infiltration, tumor mutational burden (TMB), microsatellite instability (MSI), immune checkpoints and neoantigen in many cancer types." (PMID 34762107, 2021). "Our findings provide novel insights into the role of THUMPD1 in pan-cancer that it may affect the prognosis of several cancer types, as well as being significantly associated with tumor immune regulation." (PMID 34762107, 2021). "Therapeutically, the copper ionophore elesclomol potently inhibited tumor growth in a Thumpd1-knockout mouse model of LUAD." (PMID 42080375, 2026). "THUMPD1 expression also correlated with tumor infiltration of various lymphocytes, immune checkpoints, TME biomarkers, such as TMB, MSI, neoantigens, MMRs and methyltransferases." (PMID 34762107, 2021). "The correlation between THUMPD1 expression and cancer progression and recurrence after tumor resection of KIRC and LIHC patients was consistent in different survival analyses." (PMID 34762107, 2021). "Following survival analyses that divided patients into high and low THUMPD1 expression indicated that earlier recurrence or metastasis after tumor resection was observed in CESC and PAAD patients with high THUMPD1 expression." (PMID 34762107, 2021). "To explore the effect of THUMPD1 on immune response in tumor tissues, we evaluated the correlations between THUMPD1 expression and TMB, MSI and neoantigen, which are reportedly prognostic biomarkers of cancer immunotherapy." (PMID 34762107, 2021). "We then addressed THUMPD1 effects on tumor cell invasion and migration by overexpressing THUMPD1 in MCF-7 and MDA-MB-468 cells or depleting THUMPD1 in MCF-7 and BT-549 cells." (PMID 28076326, 2017). "Moreover, we explored the correlation between THUMPD1 expression and immune cell infiltration, tumor microenvironment (TME) biomarkers and immune checkpoint genes." (PMID 34762107, 2021). "GSEA results showed the enrichment of high THUMPD1 expression in mTOR signaling pathway, neurotrophin signaling pathway and phosphotidylinositol signaling system, which all stimulate aberrant cell metabolism, angiogenesis and malignant progression of tumor." (PMID 34762107, 2021). "Alternatively, THUMPD1 may promote tumor invasion as a NAT10 downstream factor." (PMID 28076326, 2017). "THUMPD1 acted as a tumor suppressor, inhibiting LUAD cell proliferation, metastasis, and tumor growth in mouse models." (PMID 42080375, 2026). "Primary tumor burden was not affected in Thumpd1+/− mice; however, metastases were significantly repressed." (PMID 39091849, 2024). "Second, currently demonstrated role of THUMPD1 is to assist formation of ac4C in RNA molecule, however, dynamic changes of ac4C level in tumor cells are not available." (PMID 34762107, 2021).
cancer (6 papers, 2017 to 2026). A tumor composed of atypical neoplastic, often pleomorphic cells that invade other tissues. "N4-acetylcytidine (ac4C) modification regulates mRNA stability and translation, but the role of its associated co-factor, THUMP domain-containing protein 1 (THUMPD1), in cancer is unknown." (PMID 42080375, 2026). "Immunofluorescence was also performed in human cancer cells to investigate the intracellular location of THUMPD1 protein." (PMID 34762107, 2021). "Cancer cells had approximately two-fold increase in THUMPD1 expression compared with corresponding normal tissues." (PMID 34762107, 2021). "Here, we analyzed the expression profiles and prognostic value of THUMPD1 in pan-cancer and gained insights into the correlation between THUMPD1 expression level and immunotherapy efficacy." (PMID 34762107, 2021). "Among these cancer types, LAML, SKCM, STAD and THYM were positively correlated with THUMPD1 expression and the remaining were negatively associated, possibly suggesting different prognosis." (PMID 34762107, 2021). "Although the present study has provided evidence for the possible role of THUMPD1 in prognosis prediction and immune regulation for many cancers, it has limitations indeed." (PMID 34762107, 2021). "In summary, THUMPD1 is differently expressed in many cancer types, and this expression is correlated with prognosis in diverse cancers, especially for KIRC and LIHC." (PMID 34762107, 2021). "According to the results, all five MMR genes were significantly correlated with THUMPD1 and the significant correlation achieved in most cancer types." (PMID 34762107, 2021). "Here, we conducted a correlation analysis between THUMPD1 expression and TILs abundance in diverse cancer types." (PMID 34762107, 2021). "We assessed the expression of four methyl transferases genes (DNMT1,2,3,4) in pan-cancer and investigated their correlation with THUMPD1." (PMID 34762107, 2021). "In the present study, we evaluated the expression of THUMPD1 and analyzed its correlation with prognosis of different types of cancer based on The Cancer Genome Atlas (TCGA) database." (PMID 34762107, 2021). "Here, we got THUMPD1 mRNA expression profiles of various normal and cancer tissues, which served as the basis of subsequent analyses." (PMID 34762107, 2021). "Based on these, our study suggests THUMPD1 as a novel biomarker to predict prognosis and immune therapy response in diverse cancer types." (PMID 34762107, 2021). "In the analyses of relationship between THUMPD1 expression and neoantigen, we found the only cancer types with significance were LUAD, BRAD and THCA, and that they were all negatively correlated." (PMID 34762107, 2021). "Further, we explored the association between THUMPD1 expression and DFI in 33 cancer types from TCGA." (PMID 34762107, 2021). "Most of the cancers (18/27) showed higher THUMPD1 expression than para-cancerous normal tissues, while there was also down-regulation in some cancers: BLCA, KIRC, LUSC, OV and UCEC." (PMID 34762107, 2021). "In most cases, cancer patients with high THUMPD1 expression are expected to respond to immunotherapy compared with those with low expression." (PMID 34762107, 2021). "Considering the interference of non-cancer related deaths during follow-up period, we also investigated the relationships between THUMPD1 expression and DSS in 33 cancer types." (PMID 34762107, 2021). "For those cancers showing higher THUMPD1 expression, THUMPD1 can be interpreted as a novel cancer biomarker." (PMID 34762107, 2021). "In the present study, THUMPD1 expression in several cancer types, including BRCA, COAD, KIRC, and LIHC, showed significant association with most ICPs’ genes." (PMID 34762107, 2021). "We also addressed the effects of THUMPD1 on cancer cell migration and invasion, and analyzed potential downstream signaling pathways." (PMID 28076326, 2017). "This proposal could also be extrapolated to other cancers showing significant correlation with THUMPD1 expression." (PMID 34762107, 2021).
cancer (continued). "Prognostic analysis was conducted to further explore the role of THUMPD1 in diverse cancer types." (PMID 34762107, 2021). "Here, with distinct prognosis in high THUMPD1 expression cohorts, KIRC and LIHC were treated as the representation to support the idea that THUMPD1 may play distinct roles in different cancer types." (PMID 34762107, 2021). "Taken together, our study proposed that THUMPD1 may be a novel predictor to evaluate the prognosis and immune therapy efficacy in diverse cancer types." (PMID 34762107, 2021). "On the other hand, there is up- or down-regulation of specific factors that may interact with NAT10 or THUMPD1 and contribute to cancer development." (PMID 34762107, 2021). "Thus, alteration of ac4C or THUMPD1 itself, the one influences cancer prognosis, immune regulation and treatment efficacy requires future investigation." (PMID 34762107, 2021). "For those cancer types with lower THUMPD1 expression, THUMPD1 may interact with cancer-specific factors or directly serve as a protective factor against cancer development." (PMID 34762107, 2021). "In the present study, we performed a systemic bioinformatics analysis on THUMPD1, and investigated the differential THUMPD1 expression in pan-cancer and its correlation with various prognostic and immune regulatory indicators, based on several public databases." (PMID 34762107, 2021). "Hence, we investigated the possible relationships between THUMPD1 expression and immune cell infiltration in 33 cancer types from TIMER." (PMID 34762107, 2021). "Overall, our results represented that THUMPD1 could function as a prognosis predictor in several kinds of cancers." (PMID 34762107, 2021). "THUMPD1 overexpression upregulated Snail and downregulated E-cadherin, suggesting that THUMPD1 may facilitate cancer invasion through Snail, which is an extremely unstable protein." (PMID 28076326, 2017). "Therefore, THUMPD1 may serve as a favorable factor that predict the efficacy of immunotherapy for many cancer types." (PMID 34762107, 2021). "Thus, THUMPD1 may recruit and regulate TILs to promote or inhibit progression of various cancer types, indicating a crucial role in cancer immunity." (PMID 34762107, 2021). "Besides, immunotherapy response could be predicted by TME subtyping that was corresponding to different THUMPD1 expression level for some cancer types." (PMID 34762107, 2021). "Hence, studies of THUMPD1 help comprehend the role of ac4C in cancer." (PMID 34762107, 2021). "Hence, our observations showed that the THUMPD1 was differently expressed in a variety of cancers, suggesting that it may play a role in cancer progression." (PMID 34762107, 2021). "Additionally, besides the role in predicting cancer prognosis, THUMPD1 may also involve in regulating the immune reactions and serve as a predictor for immunotherapy efficacy." (PMID 34762107, 2021). "Distinct from the results of pan-cancer analysis of NAT10, our proposition demonstrates the difference between NAT10 and THUMPD1 in clinical and immunological function, though they both serve as the writing tools of ac4C." (PMID 34762107, 2021). "Our results revealed that the three top-ranking cancer with highest infiltration score were COAD, KIRC and LIHC, all positively correlated with THUMPD1 expression." (PMID 34762107, 2021). "Based on the mRNA expression pattern, we performed Western blotting to investigate the protein expression pattern of THUMPD1 in KIRC and LIHC, the representative cancer types showing opposite expression alteration in database-derived analysis." (PMID 34762107, 2021). "In the present study, we explored the correlation between THUMPD1 expression and ICP genes in pan-cancer to assess the possible function of THUMPD1 in immunotherapy." (PMID 34762107, 2021).